LMBR1 (limb development membrane protein 1)
Description:
Putative membrane receptor.
Synonyms: C7orf2; DIF14; ACHP; FLJ11665; ZRS; PPD2; THYP; TPT; TPTPS
Tractability: Antibody: UniProt predicts a signal peptide or a membrane-spanning region; its Gene Ontology location is reachable by antibodies, with medium confidence. PROTAC: ubiquitination databases record sites on it.
Gene: Protein-coding gene on chromosome 7 (156,668,946 to 156,893,225, reverse strand). Ensembl gene ENSG00000105983.
Subcellular location: Membrane
Subcellular location (Human Protein Atlas): Cytosol
Gene Ontology:
Molecular function: protein binding; transmembrane signaling receptor activity
Biological process: signal transduction
Cellular component: plasma membrane; membrane
Genetic constraint (gnomAD): Loss-of-function variants: 18 observed, 19.32 expected, observed/expected ratio (o/e) 0.93, 90% interval 0.64 to 1.38. The upper end of that interval is the gene's LOEUF score, 1.38, which puts it in group 5 of 6, group 1 being the genes least tolerant of losing a copy. Missense variants: 248 observed, 244.37 expected, observed/expected ratio (o/e) 1.01, 90% interval 0.91 to 1.13. Synonymous variants: 90 observed, 92.29 expected, observed/expected ratio (o/e) 0.98, 90% interval 0.82 to 1.16.
Homologues: Orthologues: chimpanzee LMBR1 (99% identical), macaque LMBR1 (99% identical), pig LMBR1 (98% identical), dog LMBR1 (97% identical), guinea pig LMBR1 (97% identical), mouse Lmbr1 (96% identical), rat Lmbr1 (93% identical), tropical clawed frog lmbr1 (81% identical), zebrafish lmbr1 (80% identical), Drosophila melanogaster lili (44% identical), Caenorhabditis elegans lmbr-1 (35% identical). Paralogues in human: LMBR1L (59% identical).
Diseases named in the same sentence as LMBR1 in open-access papers:
LMBR1 is named in the same sentence as 11 diseases in open-access papers, as found by Europe PMC text mining. Sharing a sentence is not in itself a finding about the gene and the disease. The quoted sentences say what the papers report.
polydactyly (5 papers, 2014 to 2021). A disease characterized by the presence of polydactyly, including syndromic and non-syndromic forms. "Thus, we confirmed that LMBR1 was the causative gene of polydactyly in the Beijing fatty chicken by using GWAS with restriction-site associated DNA based markers and resequencing." (PMID 28489934, 2017). "This SNP was in close proximity to other candidate genes for polydactyly, 113.9 kb downstream of sonic hedgehog (SSH) and 240.7 kb upstream of limb region 1 homolog (mouse) (LMBR1)." (PMID 24752238, 2014). "The genes aristaless-like 4 and limb development membrane protein 1 known for polydactyly in dogs were not included in the candidate selected regions identified in the Lundehund." (PMID 25860808, 2015).
Acheiropodia (2 papers, 2016 to 2021). "Acheiropodia, congenital limb truncation, is associated with homozygous deletions in the LMBR1 gene around ZRS, an enhancer regulating SHH during limb development." (PMID 33863876, 2021). "Acheiropodia is associated with homozygous deletions in the LMBR1 gene around ZRS, an enhancer regulating SHH during limb development, but how these deletions lead to this phenotype is unknown." (PMID 33863876, 2021). "Deletions in exon 4, and in portions of intron 3 and 4 of chicken LMBR1, may cause the oligozeugodactyly mutant phenotype, which is similar to that of humans affected with acheiropodia." (PMID 26859147, 2016). "While exon 4 of LMBR1 was deleted in the individuals with acheiropodia, it is likely not the cause of this phenotype." (PMID 33863876, 2021). "However, the ZRS is completely intact in the Brazilian individuals with acheiropodia who are homozygous for the LMBR1 exon 4 deletion, suggesting that other functional units associated with SHH limb expression may be disrupted by this deletion." (PMID 33863876, 2021).
syndactyly (2 papers, 2020 to 2022). A disease characterized by the presence of syndactyly, including syndromic and non-syndromic forms. "Autosomal dominant syndactyly type IV (SD4) is a rare form of syndactyly, caused by heterozygous mutations in a sonic hedgehog (SHH) regulatory element (ZRS) which resides in intron 5 of the LMBR1 gene on chromosome 7q36.3." (PMID 32184803, 2020). "Candidate gene studies on HOXD13, LMBR1, FGF16, BHLHA9, to understand their contribution to both cutaneous and synostosis syndactyly phenotypes, could enhance screening." (PMID 35549993, 2022).
gastrointestinal stromal tumor (1 paper, 2021). "While according to a gene expression study about gastrointestinal stromal tumor, LMBR1 might be a tumor progression promoter in GISTs by regulating the expression of nuclear BMI155." (PMID 34021184, 2021).
laurin-Sandrow syndrome (1 paper, 2021). Laurin-Sandrow syndrome (LSS) is characterized by complete polysyndactyly of the hands, mirror feet and nose anomalies (hypoplasia of the nasal alae and short columella), often associated with ulnar and/or fibular duplication (and sometimes tibial agenesis). "Laurin-Sandrow syndrome is supposed to be an autosomal dominant disorder and the gene associated is said to be limb development membrane Protein 1 (LMBR1)." (PMID 34887989, 2021).
leukemia (1 paper, 2021). A malignant (clonal) hematologic disorder, involving hematopoietic stem cells and characterized by the presence of primitive or atypical myeloid or lymphoid cells in the bone marrow and the blood. "We evaluated the nuclear location of the chromosomal region surrounding MNX1 in the leukemia K562 cell line by FISH, and assessed the transcriptional activity of genes mapping in same region (i.e., LMBR1, NOM1, MNX1, UBE3C, and PTPRN2) by qRT-PCR." (PMID 33652823, 2021).
LMBR1 also shares sentences with these, for which no sentence is quoted: tumor (2 papers); Behcet’s syndrome (1); cancer (1); melanoma (1); triphalangeal thumb polysyndactyly (1).